MED1 (mediator complex subunit 1)
Diseases named in the same sentence as MED1 in open-access papers (continued):
Sharing a sentence is not in itself a finding about the gene and the disease.
tumor (continued). "For example, miR-1291 restoration repressed tumorigenesis in prostate and pancreatic xenograft tumor models via inhibition of Mediator of RNA polymerase II transcription subunit 1 (MED1), N-methylnicotinamide (NMN)." (PMID 33343622, 2020). "In tumor-free urothelium, the expression of MED1 was present in both cellular compartments, nucleus and cytoplasm." (PMID 28367434, 2017). "In total, MED1 seems to act in a tumor-specific manner, whereby MED1 up- or downregulation can enhance tumorigenicity." (PMID 28367434, 2017). "MED1 plays an important role in mediating resistance to the pure anti-estrogen fulvestrant both in vitro and in vivo and knockdown of MED1 potentiated tumor growth inhibition by fulvestrant." (PMID 27506935, 2016). "In vivo, Med1, Med14, Med21, and Cdk8 have been shown to be required in hair follicle stem cells, plant meristem, mouse blastocysts, and tumor cells, respectively." (PMID 25772472, 2015). "Our data therefore suggest that MED1 is derived from a large cell anaplastic Group 4 tumour with MYCN amplification." (PMID 24887326, 2014). "Using an orthotopic xenograft mouse model, we found that knockdown of MED1 significantly reduced tumor growth in mice." (PMID 23936234, 2013). "And MED1 overexpression suppressed CD8+ T-cell-mediated antitumor immunity of tumor-bearing mice." (PMID 39343952, 2024). "Furthermore, MED1 modulated the expression of programmed death-ligand 1 (PD-L1) through the Notch signaling pathway, consequently impacting the tumor-killing capacity of CD8+ T cells in the tumor microenvironment." (PMID 39343952, 2024). "While the expression levels of GRB7, MIEN1, ERBB2 and FBXL20 were considerably greater in tumour tissues than in normal tissues (p < 0.001 or p < 0.01), the expression levels of MED1 and CDK12 were significantly lower in tumour tissues than in normal tissues (p < 0.001)." (PMID 37525498, 2023). "Moreover, the tumors of MED1-mutant mice grew slower and also had an overall lower tumor weight when compared to the controls." (PMID 35205279, 2022). "Notably, western blot analysis of engrafted tumor tissues showed that atuveciclib markedly decreased MED1 phosphorylation." (PMID 35394046, 2022). "To study whether MED1 overexpression affects tumor cell EMT, we performed real-time PCR and found the expression of several EMT-related genes, including twist, snail, and slug, were upregulated in the MMTV-HER2/MMTV-MED1 tumors." (PMID 33691110, 2021). "To assess whether MED1 overexpression affects tumor lung metastasis, we carried out H&E staining to analyze the metastatic lesions in the lung serial section of MMTV-HER2 and MMTV-HER2/MMTV-MED1 tumor-bearing mice." (PMID 33691110, 2021). "In addition, the effects of trastuzumab and fulvestrant, either as single agents or in combination on tumor growth as well as on expression of the protein p-MED1 expressed in in vivo mouse xenograft models was also examined." (PMID 28045951, 2017). "Interestingly, MED1 was found to play a role in the tumor response to anti-HER2 treatment as well." (PMID 35800368, 2022). "Notably, we identified new downstream target genes in 925 upregulated genes, including ZEB1, POU5F1, and MED1, which could be important factors in tumor metastasis and the maintenance of CSCs." (PMID 30674889, 2019). "Importantly, knockdown of MED1 further potentiated tumor growth inhibition by fulvestrant." (PMID 23936234, 2013). "Thus, elevated expression of MED1 in tumor cells may enhance the progression of OSCC." (PMID 39343952, 2024). "BRD4 inhibition by JQ1 was a typical example of interfering LLPS of MED1/BRD4 at super enhancer that disrupted down-stream signaling and inhibited tumor cell proliferation." (PMID 37917664, 2023). "In this study, we have generated MED1 mammary-specific overexpression transgenic mice and crossed them with the well-established MMTV-HER2 tumor mouse model." (PMID 33691110, 2021).
tumor (continued). "Importantly, our MMTV-HER2/MMTV-MED1 mouse model reported here will not only allow for better understanding of the molecular mechanisms of HER2/MED1 in tumorigenesis but also offer a more clinically relevant tumor model where both HER2 and MED1 are overexpressed for preclinical trials." (PMID 33691110, 2021). "Further analysis also showed a significant negative correlation between MED1 and miR-205 levels in these tumor samples." (PMID 39682180, 2024). "Our results show that MED1 regulates the expression of the BRCA1-dependent transcripts p21 and GADD45α, suggesting that MED1 may contribute to the anti-tumor cell cycle regulatory function of BRCA1." (PMID 36229463, 2022). "To investigate whether MED1 overexpression plays a role in these processes, we examined the effect of MED1 overexpression on MMTV-HER2 tumor response to lapatinib treatment in vivo." (PMID 33691110, 2021). "These authors proposed an epigenetic explanation for BED inhibitor resistance in TNBC cells, whereby the PP2A tumour suppressor gene is inactivated, leading to hyperphosphorylated BRD4 which binds more strongly to MED1 and allows for bromodomain-independent chromatin recruitment." (PMID 31886177, 2019). "In this study we show that the microRNA hsa-miR-137 (miR137) tumor suppressor regulates expression of an extended network of transcriptional coregulators including KDM1A/LSD1/AOF1, KDM2A/JHDM1A/FBXL11, KDM4A/JMJD2A, KDM5B JARID1B/PLU1, KDM7A/JHDM1D/PHF8, MED1/TRAP220/DRIP205 and NCoA2/SRC2/TIF2." (PMID 26461474, 2015). "Given the pivotal role of CD8+ T cells in the anti-tumor immune response, it is postulated that MED1 may modulate PD-L1 expression via the Notch signaling pathway, leading to the suppression of CD8+ T cell function, thereby facilitating immune evasion and ultimately promoting tumor progression." (PMID 39343952, 2024). "In general, TCGA RNA-seq data showed that expression of MED1, MED4, and MED14 are not lost in tumors, but varies considerably between tumor specimens compared normal." (PMID 31695025, 2019).
infection (4 papers, 2013 to 2025). The state of being infected such as from the introduction of a foreign agent such as serum, vaccine, antigenic substance or organism. "Upon infection with either Ad/PIMT or Ad/Med1 the glucose output was increased compare to that of Ad/LacZ infection, which was completely abolished in the presence of the MEK/ERK inhibitor." (PMID 24358311, 2013). "Next, QRTMs elegantly accessed the epigenetic states and functional features of viSEs assembly and validated H3K27ac, MED1, DNaseI, RNA pol II, CBP, IRF3, and p65 (co)-occupancies prior to and upon virus-infection." (PMID 40131776, 2025). "Notably, 12 of these TFs exhibited distinct phosphorylation patterns upon infection, including MED14, SIN3A, BCL6, cJUN, NFATC1, STAT3, RUNX3, GTF2F1, MED1, JUNB, TLE3, and FOSL2." (PMID 40368139, 2025). "The overlapping ratio of BRD4 and MED1 puncta and the DNA-FISH signal of GBP gene family region is significantly increased after infection, suggesting the GBPs gene region tends to relocate into LLPS transcription factory zone to efficiently initiate this immune-defense gene expression." (PMID 36195603, 2022).
blood cancer (1 paper, 2021). "Promoters with relatively increased Med1 and Cdk8 are enriched for chromatin organization and immunity-related genes in the MM1S blood cancer cell line, for differentiation and apoptosis genes in human embryonic stem cells (hESCs), and stress responses in HCT116 cells." (PMID 34515029, 2021).
gastrointestinal tumor (1 paper, 2020). "Inactivation of MED1 increases C>T transition mutations and promotes gastrointestinal tumor formation." (PMID 33251127, 2020).
MED1 also shares sentences with these, for which no sentence is quoted: cardiovascular disease (2 papers); cervical carcinoma (2); glioblastoma (2); myeloma (2); non-small cell lung carcinoma (2); acute liver failure (1); arrhythmogenic right ventricular cardiomyopathy (1); autoimmune disease (1); autoimmune thyroid disease (1); diabetes (1); epilepsy (1); Epstein-Barr virus infection (1); Fibroadenoma (1); gastric cancer (1); hemorrhage (1); hyperplasia (1); medulloblastoma (1); myocardial infarction (1); neurological disorders (1); pancreatic cancer (1); placental insufficiency (1); prostate intraepithelial neoplasia (1); skin cancer (1); squamous cell carcinoma (1); squamous cell neoplasm (1); systemic lupus erythematosus (1); T-cell acute lymphoblastic leukaemia (1); thrombosis (1); thyroid carcinoma (1); α thalassemia (1).